AURKA (aurora kinase A)
Diseases named in the same sentence as AURKA in open-access papers (continued):
Sharing a sentence is not in itself a finding about the gene and the disease.
cancer (continued). "Evidence has indicated that some PC-related protein dysfunction could promote cancer development, such as PLK1, PLK4, AURKA, and so on." (PMID 37101292, 2023). "Concerning immune inhibitors, AURKA displayed a positive correlation with IL10RB in most cancers but a negative correlation in COAD." (PMID 37965456, 2023). "Notably, the inhibition of AURKA has been shown to reshape the TIME by depleting tumor-promoting myeloid cells and enriching anti-cancer T-lymphocytes, leading to the regression of mammary tumors in mice." (PMID 37965456, 2023). "There are accumulating lines of evidence supporting the nonmitotic function of high levels of AURKA in cancer cells." (PMID 35326553, 2022). "We then looked at AURKA expression in ACC and other cancers to see if it had any predictive value." (PMID 36685952, 2022). "Almost all the FRGs in signaling pathways of pan-cancer, STMN1, RRM2, HELLS, FANCD2, and AURKA could significantly activate the cell cycle, but inhibit EMT, DNA damage response, hormones ER, RAS/MAPK, and RTK." (PMID 36349201, 2022). "Different studies seem to conclude that AURKA AS plays a role in cancer, although none go so far as reporting an AURKA AS-dependent mechanism of pathogenesis." (PMID 36067794, 2022). "We finally identified 4 mRNAs (AURKA, ASNS, ESR1 and SLC39A6), 3 miRNAs (has-let-7b-5p, has-mir-10a-5p and has-mir-17-5p), and 4 lncRNAs (SNHG16, CKMT2-AS1, NEAT1 and PSMA3-AS1), all of which have been reported in cancer." (PMID 36506097, 2022). "Despite AURKA has been shown to be an oncogene in many cancers, till date, the role of AURKA in NPC is not well characterized." (PMID 36072667, 2022). "Overall, the findings suggest that AURKA could be used to predict the prognosis of ACC and other cancers." (PMID 36685952, 2022). "In addition, research has shown that three members of the Aurora kinase family (AURKA, AURKB, and AURKC) play an important role in cancer cell migration and tumor progression." (PMID 36482411, 2022). "Meanwhile, AURKA PROTAC cocktail more effectively degrades AURKA and induces cancer cell apoptosis." (PMID 35652200, 2022). "For example, the imprinted gene GNAS and the non-imprinted gene AURKA, both important in cancer pathogenesis, had nearly identical copy number in our data (ρ = 0.964, p0 < 2 × 10–308)." (PMID 36461044, 2022). "For example, ASPM, ECT2, AURKA, BIRC5, CENPF, and EZH2 are amplified in several cancers." (PMID 36612203, 2022). "For example, the AURKA inhibitor MLN8237, the BIRC5 inhibitor YM155 and the MELK kinase inhibitor OTS167 have been tested in clinical trials for different types of cancers, and a TTK kinase inhibitor has also shown anti-cancer activity." (PMID 36612203, 2022). "Assays with bicistronic RNA constructs revealed that AURKA 5′UTR contains an IRES element, whose activity is regulated in a cell cycle-dependent manner and peaks at G2/M phase in immortalized and cancer cells only, where AURKA cap-dependent translation remained unchanged." (PMID 36067794, 2022). "AURKA promotes tumorigenesis by participating in cancer cell proliferation, epithelial–mesenchymal transition (EMT), metastasis, apoptosis, and the self-renewal of cancer stem cells." (PMID 36291769, 2022). "Although several compounds that target aurora kinase A are under development, no aurora kinase A inhibitors have been approved for patients with cancer due to the narrow therapeutic window and adverse side effects." (PMID 35745617, 2022).
cancer (continued). "AURKA is overexpressed in cancer cells but not in normal tissues, making it a potential target for immunotherapy." (PMID 35664691, 2022). "Moreover, AURKA regulated epithelial-mesenchymal transition and cancer stem cell properties in HCC to promote cancer metastasis." (PMID 33750838, 2021). "Because of their role in EMT-mediated cancer cell plasticity, drug resistance and ultimately poor clinical outcome, TGF-β and AURKA oncogenic pathways represent attractive druggable targets, and several small molecule inhibitors of TGF-β and AURKA activity are under clinical investigation." (PMID 33674749, 2021). "Many studies have shown that AURKA can phosphorylate AKT and promote EMT transition of cancers." (PMID 34131100, 2021). "Targeting both AURKA and AURKB in tumors of these cancer types may exert considerable antitumor effects." (PMID 33451333, 2021). "Thus, both catalytic and noncatalytic activities play a role in AKT function and, similar to AURKA, AKT dysregulation plays a role in many major disorders, including cardiovascular and metabolic diseases and cancer." (PMID 34944109, 2021). "It has been documented that AURKA promotes tumor progression by enhancing cell cycle progression, cell survival, genomic instability, epithelial-mesenchymal transition (EMT) and stem-like properties of cancer cells." (PMID 34332577, 2021). "In this study, we aimed to define whether TGF-β-induced cancer cell plasticity and enrichment of chemoresistant ALDH1high TNBC cells were mediated by the mitotic kinase AURKA that also plays a key role in tumor progression." (PMID 33674749, 2021). "Since the expression level of the AURKA gene has not been exactly determined in some types of cancers yet, the RNA‐seq data in the TCGA database were employed to evaluate the expression of AURKA in the 13 most prevalent cancers." (PMID 34337875, 2021). "We showed that fostamatinib (which can target PLK1 and other over-expressed serine/threonine kinases such as AURKA, MELK, NEK2, and TTK) is more active against cancer lines with more pronounced signatures of invasion (e.g., extracellular matrix organization/degradation)." (PMID 34680307, 2021). "But, it still fails to draw a significant relationship between AURKA and cancer stages (data not shown)." (PMID 33967624, 2021). "Previous and ongoing clinical studies of AURKA inhibitors in cancer have not strongly focused on tumor suppressor status." (PMID 34050264, 2021). "Aberrant AURKA expression/activity is required to promote tumor progression because of its central role in mediating TGF-β-induced SNAI1 gene expression, cancer cell plasticity, and the enrichment of ALDH1high cells harboring high self-renewal capacity and intrinsic chemoresistance." (PMID 33674749, 2021). "However, it is clear that the impact of HDAC inhibition on AURKA, AURKB, and AURKC expression is significant and should be used as an additive strategy for inducing cell cycle arrest and cell death in cancers where the AURK family of proteins are elevated." (PMID 34066975, 2021). "Cell mitosis restricts the fast proliferation of cancer cells, but most cancer cells overexpress mitosis-related proteins such as AURK family member AURKA and AURKB to affect chromosome segregation and cell cycle and cause unequal distribution of genome, producing aneuploid cells in cancers." (PMID 33612479, 2021). "AURKA has also been shown to negatively regulate FOXO1 at the transcriptional level, indicating that FOXM1 can indirectly regulate FOXO expression via AURKA to sustain its expression and activity in cancer cells." (PMID 32372224, 2020). "The expression of AURKA and AURKB during the G2/M phase transition is tightly coordinated with histone H3 phosphorylation while the overexpression of both kinases is observed in a variety of human cancers." (PMID 32138169, 2020).
cancer (continued). "Taken together, these results suggested that a protein network including AURKA, RAD54L, CDC45, and ESPL1 proteins, key molecules of pathways deregulated in cancer, could represent a common regulatory signature to all BC subtypes." (PMID 32932728, 2020). "We also show that allosteric but not catalytic AURKA inhibitors sensitize cancer cells to inhibition of the CDC7 kinase subunit of the replication-initiating factor DDK." (PMID 32652013, 2020). "Diagnostic accuracy analysis of these DEGs in TCGA datasets COAD and LUAD showed that a gene panel that consists of CALU, AURKA, and MCM2 could successfully distinguish cancer tumors from healthy samples." (PMID 32469983, 2020). "AURKA inhibition has shown efficacy in reducing cancer burden in clinical trials, however, no AURKA inhibitor has been approved by the FDA, primarily because AURKA inhibition is toxic to normal cells." (PMID 33158056, 2020). "Additionally, comparison of CALU, AURKA, and MCM2 proteins between healthy samples, early and advanced tumors showed that the level of these proteins was increased through normal–carcinoma transition in both types of cancers." (PMID 32469983, 2020). "While genetic amplification of AURKA has been described in cancer, its occurrence is low and does not match the observed high frequency of AURKA overexpression in many cancer types." (PMID 31740746, 2019). "Specifically, AURKA and TPX2 together with MYC appear to act as driver genes in MYC-driven cancers." (PMID 30177840, 2019). "Expression of HPRT1, Jag2, AURKA, and PGK1 were elevated when compared to normal samples, and HPRT1 and PGK1 showed a stepwise elevation in expression that was significantly related to cancer grade." (PMID 30679932, 2019). "The gene expression levels of cyclin B1 (CCNB1), cyclin B2 (CCNB2), Aurora A (AURKA), Aurora B (AURKB), and PLK-1 (PLK1) were increased from stages 1 to 4; however, the genes for D-type cyclins were expressed in a stable manner across the cancer stages." (PMID 30235818, 2018). "We discovered that AURKA modulated the expression and activity of PARP, a crucial mediator of DNA repair that is a target of therapeutic interest for the treatment of ovarian and other cancers." (PMID 28881569, 2017). "While a number of conventional therapeutic candidates are under development, there is as yet no reliable, universal strategy for treatment of AURKA-positive cancers." (PMID 27271876, 2016). "Our predicted results corroborate with the established roles of AURKA and CCNB1 in cancers." (PMID 26317392, 2015). "In addition, this case showed carcinoma-specific amplification of 7p (EGFR and BRAF) and 20q (ASXL1, AURKA, and GNAS), which were observed as clonal amplification for the three MSS cases without ERBB2 amplification." (PMID 26336987, 2015). "Furthermore, we find that AURKA activity is critical to the propagation and self-renewal of sphere-enriched MPNST cancer stem-like cells." (PMID 23328114, 2013). "Many groups have studied AURKA protein expression by IHC in CRC and other cancers." (PMID 22240781, 2012). "They found that shortly after treatment, some cancer cells enter a quiescent state with low KRAS activity, while others bypass inhibition by producing newly synthesised KRASG12C, which is maintained in an active, drug‐insensitive state via EGFR‐ and AURKA‐driven signalling." (PMID 41025426, 2025).
cancer (continued). "Importantly, despite numerous known cancer-specific substrates of AURKA, it has not been targeted in combination with its substrates." (PMID 39334449, 2024). "Similarly, AURKA inhibition is synthetically lethal in tumors lacking certain tumor suppressors, which can be utilized to develop highly effective cancer-specific drugs." (PMID 39334449, 2024). "Weak relationships were generally found across all the cancers, apparently inconsistent with a hypothesis that AURKA mRNA is a major target of hsa-let-7a unlike other oncogenes like RAS and MYC." (PMID 39527514, 2024). "However, the exact mechanism that determines the positive regulation of AURKA by TUG1 still remains unknown both in HCC and other cancers." (PMID 39598228, 2024). "Overall, the diverse results on AURKA cancer-specific SLR across studies are not yet conducive to a unifying hypothesis for the APA-mediated regulation of AURKA." (PMID 39527514, 2024). "Nevertheless, the downsides of targeting AURKA, in a highly heterogeneous cancer such as HCC, cannot be discounted, since not all tumors may be driven by AURKA dysregulation." (PMID 39598228, 2024). "Although this correlation is not absolute, it suggests that targeting PLK1 and AURKA could be effective in cancers characterized by high MYC family gene expression." (PMID 39085197, 2024). "Besides AURKA mitotic functions, other non-canonical and kinase-independent activities have been gradually discovered in cancer cells." (PMID 36839989, 2023). "The induction of AURKA overexpression in vitro did not demonstrate the capacity of transforming cell lines or generating malignant tumors in murine models, so Aurora A might rather be a promoting factor than an oncogene." (PMID 36387232, 2022). "Recently, novel oncogenic roles of AURKA have been uncovered that are independent of the kinase activity and act within multiple signalling pathways, including cell proliferation, survival and cancer stem cell phenotypes." (PMID 36067794, 2022). "Interestingly, Ili-A suppressed the binding of EZH2 to promoter regions in AR/serine/threonine polo-like kinase-1/aurora kinase A. Moreover, Ili-A could enhance the anticancer activity of enzalutamide in CRPC cancer models." (PMID 34776951, 2021). "Indeed, allosteric but not catalytic AURKA inhibitors sensitize cancer cells to inhibition of the CDC7 kinase subunit of the replication-initiating factor DDK." (PMID 32652013, 2020). "Characterization of centrosome abnormalities in various cancer cell lines has revealed that supernumerary centrosomes, when devoid of centrioles, were unable to nucleate microtubules despite the presence of sufficient gamma-tubulin, pericentrin, PLK1 and AURKA proteins." (PMID 29370237, 2018). "Based on current researches and observations, MLN8237 (Alisertib), one of AURKA selective inhibitor, and the AURKB selective inhibitor AZD1152 are successfully attracted researchers attention and are undergoing III clinical trials due to their potential dominant suppression for cancer treatment." (PMID 28147341, 2017). "Recently, compelling evidence indicates that AURKA can act as a novel and promising antineoplastic target; its selective inhibitor, ALS, is a small molecule which has demonstrated the potent anticancer effect in the treatment of various types of cancer in preclinical and clinical studies." (PMID 26729093, 2015). "CKS2 (chr9q22.2), CEP55(chr10q23.33), UHRF1 (chr19p13.3), RRM2 (chr2p25.1), AURKA (chr20q13.2), FLJ39632 (chr14q11.2), FAM83D (chr20q11.23), NEK2 (chr1q32.3) and MAD2L (chr4q27) were all located on PCSRs and showed over-expression in the 9, 8, 10, 9, 8, 9, 9, 8 and 9 types of cancers, respectively." (PMID 24796549, 2014). "Thus, mitotic and non-mitotic roles for AURKA are likely to regulate the self-renewal and differentiation of sphere-enriched cancer stem-like cells, mESC self-renewal, and reprogramming of somatic cells to produce human induced pluripotent stem cells." (PMID 23328114, 2013).
cancer (continued). "The low correlation observed between AURKA expression and ki67 proliferation marker (33-40% with transcript and protein respectively) assert that the AURKA up-modulation identified in NSCLC was not only due to a higher proliferation rate but suggests its involvement in cancer pathogenesis." (PMID 21718475, 2011). "The analysis of immunohistochemical data revealed that UBE2C and AURKA expression levels are higher in undifferentiated tumors of cervical (p < 0.0001 and p < 0.004, for UBE2C and AURKA respectively) and breast (p < 0.001 and p < 0.0001, for UBE2C and AURKA respectively) cancer samples." (PMID 20630075, 2010). "This variability could stem from differences in the functions of AURKA and its downstream targets in various tumor types, akin to other genes such as DKK1 and Fam20C, which exhibit varying prognostic implications in different cancer types within pan-cancer studies." (PMID 37965456, 2023). "The three non-imprinted genes at 20q11-q13.32 examined in our study, AURKA, MYBL2, and ZNF217, have a strong influence on cell cycle, proliferation, signaling, survival, and differentiation of malignant cells and on cancer progression, and they have been implicated in cancer drug resistance." (PMID 36461044, 2022). "However, increased AURKA protein is not accompanied by changes in mRNA abundance in some cancers." (PMID 36067794, 2022). "Taken together, significant downregulation of AURKA by DCCT may provide additional strategies to combat MM, because it may either prohibit tumorigenesis through inhibiting chromosome segregation anomalies or improve the sensitivity of cancer cells to chemotherapeutics in the clinic." (PMID 32978717, 2021). "Moreover, it is not clear whether AURKA could be a potential therapeutic target in this type of cancer." (PMID 24901229, 2014). "In terms of immune-activated genes, AURKA exhibited positive correlations with MICB, PVR, CD276, and ULBP1 and negative correlations with C10orf54 in most cancers." (PMID 37965456, 2023). "We further investigated the relationship between AURKA and chemokines and their relevant receptors, revealing a significant negative correlation between AURKA and CCL14 in most cancers." (PMID 37965456, 2023). "Curcumin has been found to decrease the AURKA protein and kinase activity in human breast chemoresistant nonmetastatic MCF-7 and highly metastatic cancer MDA-MB-231 cells." (PMID 35699421, 2022). "AURKA and IDH3B are not present in any of the lists of cancer genes, whereas CDK8, MARCH7, YAP1, and YES1 are found among the more than 9000 candidate cancer genes identified by forward genetic screens in mice." (PMID 33427197, 2021). "Although not identified in each of the five cancer type datasets, yet the enrichment of significant number of downstream target substrates assures probable activation of NEK2 and AURKA across the five cancers." (PMID 32033228, 2020). "The immunohistochemical staining results from HPA database indicated significantly higher positivity for AURKA, CCNB1, CCNF, and EXO1(Not found in HPA database) in cancer tissues than in adjacent normal tissues." (PMID 31087508, 2019). "As an additional method of confirming if RALA phosphorylation does not affect RALA activation in these cancers, we asked if VMLN-mediated inhibition of AURKA (that was seen to differentially affect RALA phosphorylation in MCF7 versus MiaPaCa2 cells) affects RALA activation differently." (PMID 40568758, 2025). "Additionally, we examined the effects of AURKA inhibition with alisertib and created a dominant-negative YAP1 Ser397 mutant to assess its impact on cancer stem cell features." (PMID 38467828, 2024). "In addition to imprinted genes, the 20q11-q13.32 chromosomal region contains multiple non-imprinted genes involved in cancer, e.g., AIB3, AIB4, AURKA (STK6), BTAK, MYBL2, PTPN1, STK15, and ZNF217." (PMID 36461044, 2022).